YIF1B (Yip1 interacting factor homolog B, membrane trafficking protein)
Description:
Functions in endoplasmic reticulum to Golgi vesicle-mediated transport and regulates the proper organization of the endoplasmic reticulum and the Golgi (By similarity). Plays a key role in targeting to neuronal dendrites receptors such as HTR1A (By similarity). Plays also a role in primary cilium and sperm flagellum assembly probably through protein transport to these compartments.
Synonyms: FinGER8; KABAMAS
Tractability: Antibody: UniProt predicts a signal peptide or a membrane-spanning region. PROTAC: ubiquitination databases record sites on it; its protein half-life has been measured.
Gene: Protein-coding gene on chromosome 19 (38,303,558 to 38,317,273, reverse strand). Ensembl gene ENSG00000167645.
Subcellular location: Endoplasmic reticulum membrane; Golgi apparatus membrane; Endoplasmic reticulum-Golgi intermediate compartment membrane
Subcellular location (Human Protein Atlas): Golgi apparatus; Vesicles
Gene Ontology:
Molecular function: protein binding
Biological process: endoplasmic reticulum to Golgi vesicle-mediated transport; protein targeting to membrane; cilium assembly; sperm flagellum assembly
Cellular component: endoplasmic reticulum; endoplasmic reticulum membrane; endoplasmic reticulum-Golgi intermediate compartment; endoplasmic reticulum-Golgi intermediate compartment membrane; Golgi apparatus; Golgi membrane; COPII-coated ER to Golgi transport vesicle
Genetic constraint (gnomAD): Loss-of-function variants: 24 observed, 33.56 expected, observed/expected ratio (o/e) 0.72, 90% interval 0.52 to 1.01. The upper end of that interval is the gene's LOEUF score, 1.01, which puts it in group 4 of 6, group 1 being the genes least tolerant of losing a copy. Missense variants: 368 observed, 420.62 expected, observed/expected ratio (o/e) 0.87, 90% interval 0.8 to 0.95. Synonymous variants: 186 observed, 183.01 expected, observed/expected ratio (o/e) 1.02, 90% interval 0.9 to 1.15.
Gene-disease validity (ClinGen):
ClinGen rates the evidence that YIF1B causes each of these diseases.
Kaya-Barakat-Masson syndrome (autosomal recessive): Definitive.
Homologues: Orthologues: chimpanzee YIF1B (99% identical), dog YIF1B (96% identical), pig YIF1B (91% identical), macaque YIF1B (91% identical), rat Yif1b (89% identical), guinea pig YIF1B (89% identical), mouse Yif1b (89% identical), rabbit YIF1B (86% identical), tropical clawed frog yif1b (68% identical), zebrafish yif1b (68% identical), Drosophila melanogaster Yif1 (42% identical), Caenorhabditis elegans yif-1 (34% identical). Paralogues in human: YIF1A (51% identical).
Diseases named in the same sentence as YIF1B in open-access papers:
YIF1B is named in the same sentence as 23 diseases in open-access papers, as found by Europe PMC text mining. Sharing a sentence is not in itself a finding about the gene and the disease. The quoted sentences say what the papers report.
cutaneous melanoma (2 papers, 2020 to 2026). A primary melanoma arising from atypical melanocytes in the skin. "We demonstrate that YIF1B drives cutaneous melanoma progression and enhances melanoma cell invasiveness." (PMID 42253503, 2026).
epilepsy (2 papers, 2020 to 2024). A brain disorder characterized by episodes of abnormally increased neuronal discharge resulting in transient episodes of sensory or motor neurological dysfunction, or psychic dysfunction. "The third complex subunit, Yif1p, has two human orthologues, YIF1A and YIF1B, andYIF1B mutations can also cause microcephaly and epilepsy, suggesting common pathomechanisms of the YIPF5,YIF1B and IER3IP1 disease-causing variants." (PMID 39115595, 2024). "A link to signaling pathways via HTR receptors is the likely reason for association of YIF1B mutations with functional changes to specific proteins in neuronal cells, causing encephalopathy, epilepsy and movement disorder." (PMID 32648580, 2020).
acute myeloid leukemia (1 paper, 2020). Acute myeloid leukemia (AML) is a group of neoplasms arising from precursor cells committed to the myeloid cell-line differentiation. "The KIRC and THCA cohorts showed similar expression levels between tumor and normal tissues, and KICH and acute myeloid leukemia (LAML) tumor tissues had decreased expression of YIF1B compared with normal tissues." (PMID 32648580, 2020).
bladder cancer (1 paper, 2025). "Other independent studies have highlighted the role of RPN1, HSPA5, and YIF1B as prognostic markers of the disease along with other sets of genes in bladder cancer." (PMID 40026699, 2025).
breast invasive carcinoma (1 paper, 2020). "In breast invasive carcinoma (BRCA) and liver hepatocellular carcinoma (LIHC), high YIF1B expression correlated with a poor disease-free interval (DFI), indicating a role in malignancy progression." (PMID 32648580, 2020).
developmental delay (1 paper, 2021). "Biallelic mutations of YIF1B could lead to an autosomal recessive neurodevelopmental disorder, Kara-Barakat-Masson syndrome (KABAMAS), characterized by global developmental delay, motor delay, ocular abnormalities, and nervous system change." (PMID 34059112, 2021).
esophageal carcinoma (1 paper, 2020). A primary or metastatic malignant neoplasm involving the esophagus. "It is also interesting that in esophageal carcinoma (ESCA), GBM, prostate adenocarcinoma (PRAD), SKCM and thymoma (THYM), expression of YIF1B was negatively correlated with most immune checkpoint molecules though, for some of them, not to a significant degree." (PMID 32648580, 2020).
inflammatory bowel disease (1 paper, 2025). A spectrum of small and large bowel inflammatory diseases of unknown etiology. "Thirteen SNPs (e.g., EXOC3: 6, SLC25A26: 1, YIF1B: 6) and intestinal microbiomes were significant features of the random forest for the prediction of inflammatory bowel disease." (PMID 40941714, 2025).
lung squamous cell carcinoma (1 paper, 2020). "Differences included identification of a significant risk effect for lung squamous cell carcinoma (LUSC) (in addition to the formerly mentioned ten types of cancers) and an inability to calculate a hazard ratio for YIF1B in LAML due to lack of related data." (PMID 32648580, 2020).
melanoma (1 paper, 2026). A malignant, usually aggressive tumor composed of atypical, neoplastic melanocytes. "Finally, the biological role of YIF1B was validated in A-375 and A-875 melanoma cell lines using qRT-PCR, wound healing, and transwell migration/invasion assays following shRNA-mediated knockdown." (PMID 42253503, 2026).
neuropathy (1 paper, 2020). A disorder affecting the nervous system that manifests with pain, tingling, numbness, and/or muscle weakness. "Yip1 Interacting Factor Homolog B (YIF1B) is a membrane protein involved in serotonin receptor (HTR) membrane trafficking and signal transmission in neuropathy." (PMID 32648580, 2020).
cancer (5 papers, 2020 to 2026). A tumor composed of atypical neoplastic, often pleomorphic cells that invade other tissues. "We examined their respective relationships with YIF1B expression in various cancer types in order to investigate a link between YIF1B activity and mutation in specific cancer types." (PMID 32648580, 2020). "With the development of bioinformatics, YIF1B was gradually exploited to predict clinical prognosis for cancer patients." (PMID 34938313, 2021). "After separating patients into two groups according to the respective median YIF1B expression for the cancer type, survival differences were significant between high and low expression groups." (PMID 32648580, 2020). "In our correlation analysis, expression of YIF1B was clearly also related to immune cell infiltration of different tumors, the highest scoring cancer types being KIRC, KIRP and LIHC." (PMID 32648580, 2020). "For LIHC in particular, the significance of YIF1B in cancer progression is highlighted by the gap of over 1000 days between survival times (with respect to DFI) of high and low expression groups." (PMID 32648580, 2020). "When comparing tumors with corresponding normal tissues, YIF1B expression was elevated in different cancer types, and this high expression was related to worse OS and death-specific survival in those cancer types." (PMID 32648580, 2020). "In the following survival analysis, cancer types with high YIF1B expression again exhibited a worse prognosis in comparison with the low expression groups." (PMID 32648580, 2020). "Taken together, the data indicate that YIF1B offers several cancers a valuable new biomarker for prognostic and immune therapy response evaluation." (PMID 32648580, 2020). "Using single variate Cox regression analysis, we assessed correlation between the respective expression level of YIF1B and OS in different cancer types, using data from TCGA database." (PMID 32648580, 2020). "Data for analysis of YIF1B mRNA expression were downloaded from the website portals: The Cancer Genome Atlas (TCGA), GTEx, Cancer Cell Line Encyclopedia (CCLE) and International Cancer Genome Consortium (ICGC), including clinical and mutational information." (PMID 32648580, 2020). "We have also demonstrated a link between YIF1B expression and TMB and MSI in some cancer types, and certain tumors also exhibit co-expression of YIF1B with the major MMR genes and methylation transferases." (PMID 32648580, 2020). "Here, we undertake a bioinformatics analysis to assess YIF1B expression in different tissues and its possible link to cancer." (PMID 32648580, 2020). "YIF1B expression was elevated in most cancer types and this high expression was indicative of poor overall survival (OS) and death-specific survival." (PMID 32648580, 2020). "The results identify YIF1B as a new prognostic marker for malignancy and an immune therapy response indicator in most cancer types." (PMID 32648580, 2020). "Although it is possible that the processes of methylation and MMR are directly influenced by YIF1B activity in specific cancer types, much more experimental evidence would be required to prove this is the case." (PMID 32648580, 2020). "We therefore re-analyzed the data for correlation between DSS and YIF1B expression among different cancers." (PMID 32648580, 2020). "YIF1B, a transmembrane protein involved in intracellular trafficking and signaling, is dysregulated in multiple cancers, but its role in SKCM remains unclear." (PMID 42253503, 2026). "Although serotonin has been linked to cancer, a role for YIF1B in tumorigenesis and cancer progression has not been previously established." (PMID 32648580, 2020). "We propose, therefore, that YIF1B could be deployed as an additional indicator for immune therapy evaluation of cancer patients after administration." (PMID 32648580, 2020).
cancer (continued). "To assess whether the immune microenvironment of tumors could be influenced by this pathway, we tested the correlation between YIF1B expression and the level of immune cell infiltration in each cancer type." (PMID 32648580, 2020). "We found that YIF1B was highly expressed in almost all cancer types." (PMID 32648580, 2020). "The following survival analyses, using patient data dichotomized for the median expression value in each cancer type, show that survival differences were all significant in OS-related cancer types, and that patients with high expression of YIF1B had worse outcomes." (PMID 32648580, 2020). "YIF1B is also a possible additional therapeutic target for LIHC, a cancer with poor prognosis, particularly if identified late." (PMID 32648580, 2020). "Of more significance, in different cancer cell lines from the CCLE database, not only are YIF1B expression levels elevated ubiquitously, but narrower ranges are exhibited compared with the range of expression in the normal tissues." (PMID 32648580, 2020). "Among those cancer types, DLBC, KICH and SARC had the highest coefficients, demonstrating a positive correlation between YIF1B expression and MSI." (PMID 32648580, 2020). "To further explore the potential of YIF1B as a novel biomarker for LIHC, a cancer for which early detection and prognosis are particularly poor, we undertook further analyses using data from the ICGC." (PMID 32648580, 2020). "Correlation of YIF1B expression with MSI was tested in 32 cancer types, of which none achieved significance." (PMID 32648580, 2020). "There was a positive relationship between YIF1B expression and immune cell infiltration in several cancer types, and YIF1B also positively correlated with TMB, MSI, and methylation in some cancer types, linking its expression to possible evaluation of therapy response." (PMID 32648580, 2020). "Interestingly, in cancer types of colon origin (READ and COAD), YIF1B expression clearly negatively correlates with all five MMR genes, indicative of a potential role for MMR regulation in colon tumorigenesis." (PMID 32648580, 2020). "Correlation analyses between YIF1B and checkpoint gene expression found a high correlation (P<0.05) with tumor necrosis factor (TNF)-related immune genes (TNFRSF4, 8, 14, 18) and CD276 (B7H3) in various cancer types." (PMID 32648580, 2020).
tumor (5 papers, 2018 to 2026). "Further correlation analyses between YIF1B expression and mutation indicators such as tumor mutation burden (TMB), microsatellite instability (MSI), and mismatch repair (MMR) were also examined by the Spearman test." (PMID 32648580, 2020). "High YIF1B coupled with activation of the IL-6/JAK pathway produces a positive feedback loop in which tumor proliferation/metastasis is enhanced, as is T cell immunosuppression, eventually culminating in profound immunosuppression and tumor growth." (PMID 42253503, 2026). "YIF1B expression also correlates with tumor infiltration by immune cells, immune checkpoint gene expression and immune therapy indicators, such as TMB, MSI, MMR genes and methylation genes." (PMID 32648580, 2020). "A correlation with disease progression rates was identified for LIHC and BRCA, for which patients with high YIF1B expression suffered from early recurrence of tumor." (PMID 32648580, 2020). "The results, particularly for KICH and KIRC, implicate YIF1B in regulation of the tumor immune response through modulation of immune checkpoint activity." (PMID 32648580, 2020). "Although our study has provided useful indication of involvement of YIF1B in tumorigenesis and regulation of the immune environment in tumor cells, it does comprise some limitations." (PMID 32648580, 2020). "Mechanistically, we showed that YIF1B impairs tumor-infiltrating CD8+ T cell function." (PMID 42253503, 2026). "YIF1B is known to participate in maintenance of Golgi architecture in tumor cells, and may thus affect immune cell differentiation through the serotonin pathway." (PMID 32648580, 2020). "Participation of YIF1B in serotonin-induced tumor growth and immune regulation has not been previously investigated." (PMID 32648580, 2020). "Having established a correlation between YIF1B expression and the mutation indicators, TMB and MSI, further investigation of links between YIF1B expression and tumorigenesis mechanisms was warranted, in particular a relationship with MMR defects and methylation of specific tumor suppression genes." (PMID 32648580, 2020). "One benefit of targeting YIF1B is that decreasing its activity may not interfere with the function of normal non-tumor cells." (PMID 32648580, 2020).
YIF1B also shares sentences with these, for which no sentence is quoted: Anxiety (1 paper); Encephalopathy (1); Kaya-Barakat-Masson syndrome (1); mesothelioma (1); microcephaly (1); movement disorder (1); ovarian serous cystadenocarcinoma (1); prostate adenocarcinoma (1); thymoma (1); uveal melanoma (1).